MGMT (O-6-methylguanine-DNA methyltransferase)
Diseases named in the same sentence as MGMT in open-access papers (continued):
Sharing a sentence is not in itself a finding about the gene and the disease.
astrocytoma (continued). "MGMT promoter is methylated in 85 and 98% of IDH mutant astrocytomas and oligodendrogliomas, respectively, and this phenotype is part of the G-CIMP signature." (PMID 40949165, 2025). "In our study, the methylation level of MGMT in astrocytoma was significantly higher than that in GBM, and the MGMT methylation level in grade 2 was significantly higher than those of grades 3 and 4 in astrocytoma." (PMID 38404571, 2024). "The MGMT gene promoter status was analyzed in 19 patients with GBM, one with neuroepithelial tumor with EP300::BCOR(L1) fusion, and one with astrocytoma CNS WHO grade 2." (PMID 39227460, 2024). "Our current research provides a clear example, where 50% (n = 11/22) of IDH-mutant G4 astrocytoma showed upregulated PRMT5 expression, and 10 of them had unmethylated MGMT-promoter." (PMID 38827324, 2024). "IDH-mutant WHO-G4 astrocytomas with upregulated PRMT5 and methylated MGMT-promoter who received only TMZ (n = 8) had the longest PFS." (PMID 38827324, 2024). "There was a statistically significant relationship between MGMT-promoter methylation and IDH in G4 astrocytoma (p-value = 0.006)." (PMID 38827324, 2024). "For IDHmut astrocytoma, Cutoff Finder and regression both identified the same VAF cutoff at which the difference in mean MGMT scores maximize (IDH VAF = 0.325, p = 0.05)." (PMID 37919784, 2023). "Cumulative mean MGMT pyrosequencing score trends are shown for IDHwt GBM, IDHmut astrocytoma, and IDHmut oligodendroglioma." (PMID 37919784, 2023). "We identified only 5 astrocytomas with 1p/19q codeletion in this study, and they all were IDH wild-type and MGMT promoter methylation samples." (PMID 29221210, 2017). "The frequency of MGMT hypermethylation was observed in 53% astrocytoma III and GBM samples, and the highest hypermethylation was observed in astrocytoma II (61.4%)." (PMID 27834917, 2016). "We analyzed the frequency of promoter hypermethylation by methylation-specific PCR (MSP) in five tumor suppressor genes (PTEN, MGMT, RASSF1A, p14ARF, and p16INK4A), in astrocytoma samples and cell lines." (PMID 22389839, 2012). "Our aim was to study the promoter methylation status of these five important tumor suppressor genes (p14ARF, p16INK4A, MGMT, PTEN, and RASSF1A), in a subset of astrocytomas and cell lines." (PMID 22389839, 2012). "Now, many other genes such as LHX9, MGMT, CDKN2A, PTEN, and P15 have been shown to be methylated in astrocytomas." (PMID 20334650, 2010). "Two other astrocytomas (samples 26 and 28) and the U87MG cell line were sequenced in the promoter of the MGMT gene: sample 26 was unmethylated and sample 28 was strongly methylated." (PMID 18298842, 2008). "Demethylation mediated inducible expression of the CDH13, MAGEA1, MGMT, p73 and RASSF1A genes was established in an astrocytoma cell line (U251), demonstrating that expression of these genes is likely regulated by DNA methylation." (PMID 15367334, 2004). "We present a case of IDH-mutant astrocytoma with a somewhat atypical molecular presentation, including a previously uncharacterized IDH2 mutation, retained ATRX expression, and lack of MGMT promoter hypermethylation." (PMID 41736408, 2026). "It is important to note that the MGMT-methylated group included a significantly higher proportion of grade 4 astrocytoma patients compared to the non-methylated group." (PMID 41476598, 2025). "Furthermore, amide proton transfer weighted imaging has recently also shown promising results in predicting MGMT in GBM and grade 4 astrocytoma." (PMID 41476598, 2025). "Furthermore, most ASTROs PNC harbour a methylated MGMT promoter, which is a molecular feature similar to conventional IDH-mutant astrocytomas." (PMID 39899075, 2025).
astrocytoma (continued). "MGMT-promoter methylation was examined in 140 IDH-wt astrocytoma patients; data were not available in 20 patients." (PMID 41466163, 2025). "Moreover, clinical data has revealed a significant difference in the overall median survival among patients with malignant astrocytoma treated with BCNU, depending on their MGMT levels." (PMID 38254819, 2024). "Rovin and Winn described a 28-year-old woman with a high-grade intramedullary astrocytoma lacking expression of MGMT whose residual tumor regressed favorably after surgery, radiation, and temozolomide, illustrating the significance of MGMT methylation status." (PMID 36147920, 2022). "Patients stratified into inflammation-high subtypes were associated with high mortality, unmethylated MGMT promoter status, IDH wild-type status, 1p19q non-codeletion status, WHO III grade, and astrocytoma histology." (PMID 36180938, 2022). "However, MGMT methylated patients not only behaved well in GBM, but also presented with prolonged survival in lower-grade astrocytomas." (PMID 30039219, 2019). "It is noteworthy that the proposed radiomics signature does not require a priori knowledge of grading information because it behaved well for distinguishing MGMT methylation status not only in a grade II-IV cohort, but also in grade II, III and IV astrocytomas, separately." (PMID 30039219, 2019). "While the methylation frequency of some of them (p14ARF, p16INK4A, and MGMT) has been widely assessed in high-grade astrocytomas, it has not been much studied in low-grade astrocytic tumors." (PMID 22389839, 2012). "The other eight cell lines (7 GBM and 1 astrocytoma grade III) did not express detectable levels of the MGMT protein." (PMID 20517307, 2010). "Furthermore, MGMT expression was not strongly altered between individual patient-matched tumors and within the vast majority of tumors of the different astrocytoma progression groups further supporting the important role of MGMT as a prognostic marker." (PMID 32604718, 2020). "In addition, we did not observe MGMT expression changes between individual patient-matched tumors within the astrocytoma progression groups A2 to A3 and A2 to G4 and only observed one down- and one upregulation of MGMT in the A3 to G4 progression group." (PMID 32604718, 2020). "Our results suggest the existence of mechanisms of inactivation different from methylation for p14ARF and p16INK4A genes, while offer doubts about the direct cause-effect relationship between promoter methylation and lack of expression of PTEN and MGMT in astrocytoma cell lines." (PMID 22389839, 2012). "Additionally, we hypothesize that the efficacy of TMZ in G4 astrocytoma may improve with the use of PRMT5 inhibitors, irrespective of the methylation status of MGMT-promoter or IDH mutational status." (PMID 38827324, 2024). "We observed MGMT promoter methylation in IDH-mutant astrocytomas of CNS WHO grade 2 less frequently than in CNS WHO grade 3 or 4 tumors, a finding which might contribute to the lack of prognostic association of the MGMT status." (PMID 38183430, 2024). "Among 246 samples assessed via DNA methylation array, 140 (57%) tested positive for MGMT promoter methylation (79 IDHwt GBMs, 32 IDHmut astrocytomas, 29 IDHmut oligodendrogliomas), while 106 (43%) tested negative (88 IDHwt GBMs, 18 IDHmut astrocytomas, 0 IDHmut oligodendrogliomas)." (PMID 37919784, 2023). "Statistically significant differences in PFS were observed among all G4 astrocytomas that expressed PRMT5 and received either TMZ or TMZ plus other chemotherapies, regardless of their IDH or MGMT-promoter methylation status (p-value = 0.0014)." (PMID 38827324, 2024). "In our current study, we have observed that there were significant differences in PFS of all G4 astrocytoma with upregulated PRMT5, receiving TMZ or TMZ plus other chemotherapeutic agents, regardless of IDH or MGMT-promoter status." (PMID 38827324, 2024).
astrocytoma (continued). "Statistically significant differences in progression-free survival (PFS) were also observed among all G4 astrocytomas that expressed PRMT5 and received either temozolomide (TMZ) or TMZ plus other chemotherapies, regardless of their IDH or MGMT-methylation status (p-value=0.0014)." (PMID 38827324, 2024). "Furthermore, no significant expression difference was observed for the MGMT gene between IDH1 mutant and wild type astrocytomas (q = 0.87)." (PMID 32604718, 2020).
colorectal cancer (99 papers, 2002 to 2025). A primary or metastatic malignant neoplasm that affects the colon or rectum. "In colorectal cancer, MGMT promoter methylation is frequently associated with microsatellite instability (MSI), a condition where DNA MMR is impaired." (PMID 40895460, 2025). "This evidence is counterintuitive as compared to prior studies in colorectal cancer, where MGMT methylation was associated with an increase of G‐to‐A KRAS point mutations." (PMID 39618336, 2024). "Researchers included colorectal cancer patients with O6-methylguanine-DNA-methyltransferase (MGMT)-deficient tumors that were also MMR-proficient and RAS-mutant in the Arethusa trial, a proof of concept trial that involved priming therapy with TMZ." (PMID 38817857, 2024). "Loss of MGMT expression has a significant impact on various types of cancers, mainly colorectal cancer." (PMID 37510370, 2023). "Here we found prominent discordance between the MGMT promoter hypermethylation status and MGMT protein expression in colorectal cancers and the associated clinical outcomes." (PMID 37387791, 2023). "The current work confirmed a significant association between ERCC1 and MGMT methylation, either alone or combined with poor prognosis, relapse and low survival in colorectal cancer patients." (PMID 37510370, 2023). "This is noteworthy because MMR-deficient colorectal cancers pose a greater risk of resistance to DNA-alkylating drugs due to overexpression of MGMT or MMR-deficiency." (PMID 25933036, 2015). "Loss of MGMT expression due to aberrant promoter methylation was shown in 40% of colorectal cancers and gliomas and 25% of non-small cell lung carcinomas, lymphomas, and head and neck carcinomas." (PMID 24151575, 2013). "Loss of MGMT expression is almost exclusively associated with methylation of CpG islands in the MGMT gene promoter region which is found in approximately 40% of colorectal cancers." (PMID 24151575, 2013). "A large number of molecular epidemiology studies have been carried out to assess the roles of the MGMT polymorphisms in various types of cancer, including lung cancer, head and neck cancer, and colorectal cancer." (PMID 24086516, 2013). "Despite evidence for involvement of MGMT in colon cancer carcinogenesis, previous studies fail to show any prognostic significance of MGMT methylation (or loss of MGMT) in colorectal cancers." (PMID 24151575, 2013). "It has been indicated that hypermethylation of the MGMT promoter may contribute to the development of colorectal cancer by promoting KRAS mutations through the inactivation of a DNA repair gene." (PMID 39218931, 2024). "Methylation of MGMT in colorectal cancer is associated with G-to-A mutations in the KRAS gene." (PMID 31695915, 2019). "Notably, MLH1 and MGMT have been previously associated with two distinct methylation landscapes in colorectal cancer that exhibited important differences in terms of KRAS and APC mutation frequency." (PMID 25960768, 2015).
colorectal cancer (continued). "MGMT Leu84Phe variants may increase lung cancer risk, especially in Caucasians, but reduce colorectal cancer risk, indicating some differences among different tumor sites." (PMID 24086516, 2013). "In addition, a previous study on colorectal cancer showed that methylation of another DNA repair gene, MGMT, is also linked to MSI." (PMID 23414134, 2013). "Furthermore, an association between MGMT methylation and the germline C to T SNP (rs16906252) within the first exon of MGMT is observed in colorectal cancer and normal colonic mucosa." (PMID 24151575, 2013). "In one report, a MGMT germline polymorphism (rs16906252 C>T) located within the transcriptional enhancer element of the MGMT promoter was strongly associated with susceptibility to CpG island methylation and gene silencing in colorectal cancer (OR = 18.0; 95% CI:6.2–52.1, p<.0001)." (PMID 22022277, 2011). "Since MMR-deficient colorectal cancers pose a greater risk of resistance to DNA-alkylating drugs due to overexpression of MGMT or MMR-deficiency, it is critical to discover a chemotherapeutic strategy that can be useful for the treatment of both MMR-deficient and MMR-proficient colorectal tumors." (PMID 21311763, 2011). "The DNA methylation patterns in the CpG island of the O6-methylguanine-DNA methyltransferase (MGMT), p16, deleted in colorectal cancer (DCC) and death-associated protein kinase 1 (DAPK1) genes were determined by sodium bisulfite treatment and subsequent methylation-specific PCR MS PCR." (PMID 19830138, 2009). "Thus, in a large study of germline genotypes (WBC) including a validation cohort, Kuroiwa-Trzmielina and colleagues found the rs16906252 alternative T-allele to be associated with an odds ratio (OR) of 3–4 for developing MGMT promoter–methylated colorectal cancer." (PMID 39980037, 2025). "The genes MutL Homolog 1 (MLH1), O6-methylguanine-DNA methyltransferase (MGMT), and cyclin-dependent kinase inhibitor p16INK4a are commonly downregulated by hypermethylation in colorectal cancer." (PMID 40357388, 2025). "A study of 244 patients with colorectal cancer analyzed the effects of epigenetic alterations on proto-oncogenes by examining the MGMT gene." (PMID 39218931, 2024). "The methylation of the O6-methylguanine-DNA methyltransferase (MGMT) promoter is an early event in colorectal cancer, occurring in approximately 40% of patients with colorectal cancer." (PMID 38627681, 2024). "In this follow-up research, we observed the interaction of these gene polymorphisms (COMT, GSTM1, GSTT1, MGMT, NQO1, and XRCC1) with different meat diets and on outcomes linked to colorectal cancer risk: ATNC levels, DNA adduct levels, and DNA strand breaks." (PMID 38337709, 2024). "Studies have demonstrated that MGMT methylation plays a significant role in colorectal cancer, influencing tumor sensitivity to alkylating agents." (PMID 39055560, 2024). "Despite different cutoffs adopted, this prevalence is lower as compared to other GI tumors like colorectal cancers where MGMT promoter methylation has been described in up to 40% of cases." (PMID 39618336, 2024). "For instance, the hypermethylation of the O-6-methylguanine-DNA methyltransferase (MGMT) gene, which encodes a DNA repair protein, precedes KRAS mutations in the onset of colorectal cancer, even when mutations in KRAS are early events in carcinogenesis." (PMID 38893242, 2024). "Some patients showed evidence of epigenetic silencing of the MGMT gene by promoter hypermethylation, which was connected to a higher frequency of activating mutations in KRAS, a proto-oncogene frequently mutated in colorectal cancer." (PMID 39218931, 2024). "Patients with advanced colorectal cancer were screened for MGMT promoter hypermethylation using methylation-specific PCR of archival tumor." (PMID 37387791, 2023). "There are several reports on the methylation profile of ERCC1 and MGMT in colorectal cancer patients from different populations." (PMID 37510370, 2023).